GSDMA (gasdermin A)
Diseases named in the same sentence as GSDMA in open-access papers (continued):
Sharing a sentence is not in itself a finding about the gene and the disease.
tumor (72 papers, 2009 to 2026). "Evidence suggests that intratumoral delivery of nanoparticle-conjugated, pre-cleaved GSDMA selectively causes tumor cell pyroptosis due to its N-terminal domains, which forms pores by binding to acidic phospholipids in cell membranes." (PMID 34910689, 2021). "A recent study showed that intratumoral delivery of nanoparticles conjugated with a precleaved form of mouse gasdermin A (GSDMA3) could cause selective tumor cell pyroptosis." (PMID 34795266, 2021). "The expression levels of GSDMB and GSDME were higher in tumor grades 2 and 3 compared to normal tissues, whereas GSDMA expression level was significantly increased in tumor grade 2 compared to normal tissues." (PMID 39607202, 2024). "The majority of PRGs were significantly elevated in tumor tissue, while GSDMA and CTSG were significantly decreased." (PMID 37221570, 2023). "The expression of all the six GSDMs (except GSDMA) was significantly higher in tumor stage 1–3 subgroups, compared with that in normal subgroups." (PMID 34731088, 2021). "The expression of all the GSDMs (except GSDMA) was significantly higher in tumor stage 1–3 subgroups, compared with that in normal subgroups." (PMID 34731088, 2021). "Therefore, our results establish GSDMA as a critical downstream mediator of RBM47-induced tumor suppression that links epithelial differentiation and pyroptosis to chemotherapy sensitivity." (PMID 41681975, 2026). "First, except for GSDMA, the other three genes were overexpressed in the tumor samples." (PMID 37561524, 2023). "Interestingly, previous results confirmed that the expression of GSDMA/B/D/E was significantly elevated in tumor tissues, while PJVK was downregulated." (PMID 35321945, 2022). "As expected, gasdermin A, C and E were found to be underexpressed or not expressed in most types of tumours, which was caused by methylation of the promoter or mRNA." (PMID 35289335, 2022). "Similarly, the mRNA expression levels of GSDMA/B/D/E were positively correlated with tumor grade." (PMID 35321945, 2022). "These evidences implied that GSDMA might be a tumor suppressor gene in gastric cancers." (PMID 36509838, 2022). "Interestingly, an expansion of GSDMA-expressing cells was found in the epidermis overlying the tumor, suggesting that GSDMA may mediate certain stress responses." (PMID 26100518, 2015). "GSDMA, GSDMB, GSDMD, and GSDME displayed significantly higher expression in tumor stage 2 and 3 than in normal tissues." (PMID 39607202, 2024). "In other investigations, GSDMA, GSDMB, GSDMC, and GSDMD have also been shown to have tumor-suppressing properties." (PMID 35769504, 2022). "Despite merely 15% tumor cells being found to perform pyroptosis, the entire 4T‐1 tumor was completely eradicated in the cooperative treatment of Phe‐BF3 and GSDMA‐NP." (PMID 36266982, 2022). "Three genes (ELANE, NLRP7, and CASP5) were downregulated, whereas seven others (GSDMC, IL1A, NOD2, GZMB, GSDMA, IL1B, and PLCG1) were overrepresented in the tumour group." (PMID 35087586, 2022). "Based on the analysis of UALCAN, the expression of all GSDM family members was increased in tumor-stage 1–3 subgroups, and the expression of GSDMA, GSDMB, GSDMC, and PJVK was higher in all four tumor-stage subgroups than in normal subgroups." (PMID 36505798, 2022). "GSDMA expression showed a significant negative correlation with the tumor purity of LIHC (p < 0.05) and a significant positive correlation with the degree of infiltration of B cells, CD8+ T cells, CD4+ T cells, macrophages, neutrophils, and dendritic cells." (PMID 38434972, 2024). "Compared with normal tissues, GSDMA and GSDMD showed higher expression levels in tumor stage 1." (PMID 39607202, 2024). "Since GSDMA and GSDME exert critical tumour‐suppressive effects on tumorigenesis, upregulation of GSDMA/GSDME and induction of GSDMA/GSDME‐related pyroptosis might be a promising therapeutic target for the treatment of cancer." (PMID 34590363, 2021).
tumor (continued). "However, it has been reported that GSDMA, GSDMC, and GSDMD have the effect of inhibiting tumor proliferation." (PMID 34778452, 2021). "Due to promoter or mRNA methylation, GSDMA, GSDMC, and GSDME are expressed at low levels or are not in tumours." (PMID 35289335, 2022). "Not surprisingly, the high expressions of GSDMA, GSDMC, GSDMD and GSDME were observed correlated with low tumor purity." (PMID 35164740, 2022). "However, the results revealed that BRQ treatment did not activate GSDMA, GSDMB, or GSDMC in tumor cells." (PMID 41144149, 2025).
cancer (47 papers, 2012 to 2025). A tumor composed of atypical neoplastic, often pleomorphic cells that invade other tissues. "We find that somatic mutations create or disrupt putative miRNA target sites in the 3′UTRs of many genes, including several genes, such as MITF, EPHA3, TAL1, SCG3, and GSDMA, which have been previously associated with cancer." (PMID 23091610, 2012). "For example, increased expression of TAL1, SCG3 and GSDMA has been observed in cancers, and somatic mutations in the 3′UTRs of these genes disrupt putative targets of miRNAs that have been associated with cancer." (PMID 23091610, 2012). "Caspase‐1 inhibits cancer cell migration, and GSDMA can regulate the pyroptosis to inhibit cancer cell development." (PMID 38800967, 2024). "This combination effectively delivers the mouse version of GSDMA, specifically Gsdma3, to various human and mouse cancer cells, including HeLa (cervical), EMT6 (mammary), and 4T1 (mammary) cells." (PMID 38304430, 2024). "Downregulation of gasdermin A (GSDMA) results in caspase-3 activation and cancer cell death through the mitochondrial apoptotic pathway." (PMID 37337018, 2023). "GSDMC, NLRP7, CASP5, PYCARD, IL18, IL1B and GSDMA were significantly upregulated in 22, 18, 18, 18, 18, 16 and 17 types of cancers, respectively." (PMID 35246158, 2022). "High expressions of GSDMA, GSDMB and GSDMC were associated with subtype C1 (Wound healing), C2 (INF-r dominant) and C6, indicating a cancer promoter role of these three members." (PMID 35164740, 2022). "GSDMA acted as a cancer-promoting gene in our study due to its overexpression in OC tissues and its negative correlation with survival time." (PMID 33828074, 2021). "GSDMA is frequently found down-regulated in human gastric and skin cancer tissues and cancer-derived cell lines." (PMID 24675552, 2014). "For example, GSDMA is primarily expressed in epithelial tissues and may play a role in inflammation regulation and cancer suppression." (PMID 39735183, 2024). "Moreover, TGFβ up-regulates GSDMA expression through lmo1, and the resultant GSDMA overexpression induces apoptosis in human cancer cell lines." (PMID 23979942, 2013). "The GSDM family includes six members, GSDMA, GSDMB, GSDMC, GSDMD, GSDME (DFNA5), and PJVK (Pejvakin, DFNB59), which can induce pyroptosis, thereby regulating the tumorigenesis of various cancers." (PMID 36505798, 2022). "Gene expression of GSDMA and GSDMD was frequently suppressed, and GSDMB was overexpressed in cancer cell lines and/or cancer tissue specimens." (PMID 23979942, 2013). "As a result, these GSDMs primarily function in basic immune responses and do not exhibit the specialized roles seen in mammals, such as GSDMA’s involvement in cancer suppression and GSDMB’s regulation of inflammatory processes." (PMID 39735183, 2024). "Within this study, the drug-sensitivity analysis uncovered a negative correlation between the expression levels of the prognostic-related genes (PRGs) utilized in the model (IL18, CASP3, GSDMA, and PLCG1) and the majority of drugs present in the cancer therapeutic response portal database." (PMID 37561524, 2023). "We observed that NLRP7 (n = 8), AIM2 (n = 10), CASP8 (n = 6), GSDMA (n = 5), GSDMB (n = 8), and GSDMC (n = 12) mainly showed hypomethylation in most cancers, and PLCG1 (n = 11), NLRP6 (n = 13), ELANE (n = 11), CASP6 (n = 5), NLRC4 (n = 12), and PYCARD (n = 8) showed hypermethylation in most cancers." (PMID 35246158, 2022). "GSDMB is located in the same chromosomal region than GSDMA; however, their expression is neither overlapping nor complementary during cancer development and progression." (PMID 24675552, 2014). "The comparative analysis of these proteins suggests that GSDMA may act as tumor suppressor gene in gastric cancer, while GSDMB could be considered as an oncogene based on its amplification and over-expression in this cancer type." (PMID 24675552, 2014).
cancer (continued). "Overall, previous literature proposed that GSDMA is considered a tumor suppressor gene according to its pro-apoptotic effect in cancer cells, while GSDMB gene, which is up-regulated in some cancer types, might have a tumor-promoting role." (PMID 24675552, 2014).
bacterial infection (6 papers, 2022 to 2025). "Other differentiation-associated genes, such as gasdermin A (GSDMA), are not required for cornification, but have indispensable functions under particular forms of stress such as bacterial infection." (PMID 36976101, 2023).
infection (6 papers, 2022 to 2025). The state of being infected such as from the introduction of a foreign agent such as serum, vaccine, antigenic substance or organism. "GSDMA was recently identified as the mediators of pyroptosis, an inflammatory cell death triggered by cytosolic sensing of invasive infection." (PMID 35672318, 2022). "Further studies are still required to reveal whether GSDMA activation occurs upon infection with other pathogens and to investigate whether and when the other murine GSDMAs (GSDMA2/3) trigger pyroptosis." (PMID 35455985, 2022). "A recent study demonstrated that human GSDMA and murine GSDMA1 are proteolytically activated by the cysteine protease SpeB after infection with the skin pathogen Streptococcus pyogenes." (PMID 35455985, 2022).
peripheral neuropathies (1 paper, 2026). "Intriguingly, while caspase‐1 triggers GSDMD‐mediated pyroptosis in various peripheral neuropathies, caspase‐1 instead activates gasdermin A (GSDMA) or gasdermin E (GSDME) in the CNS disorders." (PMID 41574659, 2026). "The roles of GSDMA, GSDMB, and GSDMC in peripheral neuropathy remain largely unexplored, representing a significant knowledge gap." (PMID 41574659, 2026).
GSDMA also shares sentences with these, for which no sentence is quoted: acute myeloid leukemia (2 papers); bladder cancer (2); breast tumors (2); deafness, autosomal dominant 5 (2); esophageal cancer (2); infectious disease (2); lung carcinoma (2); age-related hearing loss (1); ankylosing spondylitis (1); atherosclerosis (1); chromophobe renal cell carcinoma (1); colitis (1); COVID-19 (1); diabetic nephropathy (1); endotoxemia (1); esophageal squamous cell carcinoma (1); hay fever (1); hearing loss (1); hidradenitis suppurativa (1); intrahepatic cholangiocarcinoma (1); kidney cancer (1); leukemia (1); melanoma (1); metabolic disorders (1); myopia (1); Pan (1); pheochromocytoma (1); rhabdomyosarcoma (1); sarcoma (1); serous ovarian cancer (1).
A further 8 diseases each share a sentence with GSDMA in 1 paper.